IL6 (interleukin 6)
Diseases named in the same sentence as IL6 in open-access papers (continued):
Sharing a sentence is not in itself a finding about the gene and the disease.
tumor (continued). "The supernatant of the tumor cell culture was assessed using ELISA assay to determine whether the IL-6 knock-out has an effect on macrophage polarization and migration as well as in tumor angiogenesis." (PMID 29100435, 2017). "Furthermore, elevated interleukin-6 (IL-6) has been observed in almost all types of tumors acting as a major pro-inflammatory mediator in tumor microenvironment." (PMID 29312621, 2017). "In addition, tumor expression of IL-6, MMP-9 and ALDH1A1 was decreased (P < 0.05) in mice treated with pHLIP-PNA3 compared to control." (PMID 28420874, 2017). "This highly increased expression of IL6 in the tumour periphery might be a result of chronic UV exposure contributing to the shift in fibroblast phenotype." (PMID 28987144, 2017). "Similarly, pro-inflammatory cytokines such as IL-6 and TNFα that are also present in the OC microenvironment, support tumour progression by influencing angiogenesis and tumour infiltration with myeloid cells." (PMID 28410380, 2017). "The tumor-infiltrating myeloid cells (CD11b+F4/80+ and CD11b+/F4/80-) and circulating monocytes (CD11b+) in blood were identified as the predominant cells producing IL-6." (PMID 29207662, 2017). "Considering the well-known effect of IL-6 on STAT3 activation and the presence of IL-6 in our tumor model, we next asked whether IL-6 produced by TAMs contributes to the proliferative advantage provided by macrophages in our co-culture system." (PMID 29207662, 2017). "Additionally, the interaction between NF-κB and PARP1 upregulates the level of pro-inflammatory cytokines like tumor necrosis factor α (TNFα) and interleukin 6 (IL6), which will also initiate tumor-promoting inflammation." (PMID 28991194, 2017). "However, there was a significant effect of tumor cell type on IL-1β (H = 29.44, p < 0.0001), IL-6 (F2, 37 = 13.68, p < 0.0001), TNFα (F2, 38 = 26.73, p < 0.0001), and CXCL1 (H = 10.86, p < 0.005)." (PMID 28811490, 2017). "Here, we hypothesize that endothelial cell-secreted interleukin-6 (IL-6) contributes to tumor progression by enhancing the migratory phenotype and survival of cancer stem cells." (PMID 29245982, 2017). "Increased glycolysis promotes tumor-associated MDSC expansion in the NPC microenvironment by triggering the activation of p65 and the NLRP3 inflammasome signaling pathway, which leads to the production of IL-1β, IL6 and GM-CSF by malignant NPC cells." (PMID 28732079, 2017). "By univariate analysis, the following parameters were considered for EFS and OS determination: tumor burden (<vs≥3.0 cm), tumor progression (low vs high), lymph node status (<3 vs≥3 or 4+) and median values of serum Shh (<vs≥36.42 pg/mL) and IL-6 (<vs≥167.90 pg/mL)." (PMID 28496132, 2017). "Interestingly, we found that perivascular-like cells from tumor tissue secreted high levels of IL-6 compared to the matched normal cells." (PMID 28878242, 2017). "This might suggest that the reduction of IL-6 expression in tumor specimens and lung specimens could be an integrated result as suppression of IL-6 secretion in both tumor cells and inflammatory cells in vivo." (PMID 28088791, 2017). "In this study, we further demonstrated that G-CSF and IL-6 could upregulate the expression of iNOS that contributes to the survival and proliferation of tumor cells by suppressing T cell activation." (PMID 28432279, 2017). "Plasma levels of IL-6 were increased in TB mice at days 15 and 20 after tumor cell inoculation." (PMID 28475119, 2017). "Interestingly, all three clinical specimens we obtained from RCC patients who were treated with TKIs prior to surgery showed strong IL-6 expression in the tumor parenchyma, although the number of the patients was quite small." (PMID 28903416, 2017).
tumor (continued). "Consistent with our in vitro data, we found that the level of STAT3 phosphorylation in Bazedoxifene treated tumor tissue was reduced comparing to vehicle group, supporting that Bazedoxifene suppressed tumor growth in nude mice through inhibition of IL-6/GP130/STAT3 signaling." (PMID 28672024, 2017). "Therefore, IL-6, as an important factor in tumor growth and metastasis, should be further discovered its role in the mechanism of sorafenib or (and) IFN-α treatments of HCC." (PMID 29100435, 2017). "We measured tumor phospho-Tyr705-STAT3 to determine whether the decrease in IL-6 levels resulted in the suppression of STAT3 activation." (PMID 28416734, 2017). "Furthermore, IL-6 supports vascular endothelial growth factor A production, resulting in enhanced tumor-angiogenesis." (PMID 28872582, 2017). "However, once the tumor cells acquire the EMT phenotype induced by IL-6 and TGF-β, they leave away from the primary sites of the microenvironment." (PMID 27992365, 2017). "Our results found that SH reduced IL-6 expression in tumor specimens and lung specimens." (PMID 28088791, 2017). "IL-6 overexpression in tumor-bearing mice was not able to induce muscle mass loss and metabolic changes when they were regularly exercised on a treadmill." (PMID 28785374, 2017). "These investigations indicated that IL-6 could induce the release of VEGF from the tumor cells promoting angiogenesis." (PMID 27903982, 2017). "IL-6 promotes tumor angiogenesis, metastasis and metabolism." (PMID 28423627, 2017). "In addition to its local effects in the tumor microenvironment, tumor-derived IL-6 can stimulate paraneoplastic thrombocytosis in patients with advanced EOC, which is also associated with poor prognosis." (PMID 28388577, 2017). "Finally, multiple curcumin treatments produced a pronounced decrease both in the proportion of positive cells and intensity of staining after immunohistochemical staining with an anti-IL6 monoclonal antibody, suggesting a change in tumor microenvironment." (PMID 28915695, 2017). "Analysis of tumor infiltrations of myeloid cells such as macrophages and neutrophils by staining for F4/80 or Gr-1 antibody, respectively, revealed that these major cellular sources of IL-6 were decreased in KCH mice following treatment with anti-H3 antibody." (PMID 28374746, 2017). "Among several cytokines, IL-6 is the most studied pro-inflammatory factor in tumor." (PMID 28676747, 2017). "In our study, since the tumor groups were compared with healthy controls, the significant increase in IL-6 concentration may be a useful marker for HPB cancers." (PMID 29410961, 2017). "IL-6 has been shown to promote tumor survival, metastasis, and angiogenesis." (PMID 29527228, 2017). "IL-6 level has been correlated with tumor progression in multiple cancer types." (PMID 29245982, 2017). "The activation of Src via phosphorylation as a result of downstream adrenergic signalling has also been identified as a key switch in tumour metastases, with Src implicated in NE-mediated vascular endothelial growth factor (VEGF) and IL-6 production, ultimately promoting invasion and metastases." (PMID 28340615, 2017). "The differences in tumour progression observed in age-matched animals may in part be explained by a reduction in tumor IL-6, pSTAT3 and TNFα levels; suggesting that the tumour cytokines play a role in AT1R-mediated tumorigenic functions." (PMID 28416734, 2017). "We found that SH decreased IL-6 production in both tumor cells MDA-MB-231 and RAW 246.7." (PMID 28088791, 2017). "Taken together, these results indicate that tumor microenvironment factors such as IL-6 may promote the expression of RNCR3 during MDSC differentiation, implying that RNCR3 may play an important role in the differentiation and function of MDSCs." (PMID 29340089, 2017). "It was hypothesised that circulating macrophages and T lymphocytes produce IL-6 in response to tumour burden, or plasma IL-6 is produced by the tumour mass itself." (PMID 28384249, 2017).
tumor (continued). "IL-6 in the plasma binds to soluble IL-6RA and this complex has elevated agonist activity at activating tumor cell surface IL-6RA, however, gp130 in the plasma binds to the IL-6/sIL-6RA complex and quenches the ability of the protein complex to act as an agonist." (PMID 28146421, 2017). "Although IL-6 could be secreted by a various sources in the tumor microenvironment, including tumor cells, tumor-infiltrating macrophages, T cells, we and others have shown that IL-6 is highly secreted in CAA." (PMID 28915700, 2017). "In our study, IL-6 was mainly expressed in CAFs, and was more highly expressed in SH-HCCs than in C-HCCs, suggesting that IL-6, induced by a senescent phenotype in CAFs, may alter the tumor stroma, which is important in the development of SH-HCCs." (PMID 28273155, 2017). "IL-6 is an important mediator of the tumor-promoting effects of inflammation." (PMID 28725043, 2017). "We found that elevation of serum IL-6 was associated with decreased OS and EFS in patients with STS, suggesting that IL-6 elevation before treatment may be related to aggressive tumor behavior." (PMID 28851899, 2017). "Tumor cells are able to induce a suppressive phenotype by STAT3-signaling which leads to secretion of IL-6 and may suppress the activity of several cell types relevant to antigen presentation and cytotoxic T-cell responses." (PMID 28402937, 2017). "These factors contribute in a cumulative way to the creation of the proinflammatory and immunosuppressor microenvironment that favors tumor proliferation The IL-6 and the IL-10 have received major attention owing to their correlation to poor prognosis and inadequate response to treatment." (PMID 28848618, 2017). "Cancer-associated fibroblasts promote tumor growth and angiogenesis through the production of several molecules, including vascular endothelial growth factor (VEGF), fibroblast growth factor (FGF), and interleukin-6 (IL-6)." (PMID 28212293, 2017). "In contrast to a direct anti-tumor effect, IL-6 has an anti-apoptotic effect, suggesting a possibility that targeting IL-6, which would block the anti-apoptotic effect of IL-6, may synergize with a chemotherapy regimen by promoting cell death." (PMID 28292326, 2017). "IL-6 was found in viable tumor cells while MCP-1 was demonstrated in macrophages or tumor matrix." (PMID 27664151, 2017). "In conclusion, based on the in vitro study, IL-6 hasno significant effect on cell proliferation and invasion, but could exert pro-apoptosis effect and up-regulate tumor derived IL-33 and VEGF-A." (PMID 29100435, 2017). "We had recently shown that IL-6 promotes tumor cell migration by regulating the FAK activation." (PMID 28978005, 2017). "Moreover, treatment of MSCs with supernatants from PC3 cells, leading to tumor-educated MSCs (TE-MSCs), increased the secretion of IL-6, CCL5, VEGF and FGF-2 by MSCs and increased their capability to increase PC3 cells clonogenic growth." (PMID 28477013, 2017). "Moreover, the effects of MEPs can supersede tumor-promoting CAFs by blocking IL-6 signaling pathways." (PMID 28506312, 2017). "We suggest that measurement of IL-6 levels may be a useful method for identifying patients who are at a high risk of STS and tumor-related death." (PMID 28851899, 2017). "IL-6 is multifunctional cytokine with a wide range of biological activities in inflammatory, immune responses, cell apoptosis and proliferation in various cells including tumor cells." (PMID 28672024, 2017). "However, we found that genetic ablation of the IL6 gene in NB-Tag mice led to similar tumor growth pattern as in their IL-6-producing counterpart, and macrophages isolated from IL6 knockout mice were just as capable of increasing NBL proliferation in vitro." (PMID 29207662, 2017).
tumor (continued). "The activation of NF-κB can be triggered by various stimuli including tumor-necrosis factor (TNF), interleukin 1 (IL-1), interleukin 6 (IL-6), endotoxins, carcinogens, tumor promoters, microbial pathogens, free radicals, lipopolysaccharide (LPS), and radiation (UV-light, X-rays, γ-rays)." (PMID 28635648, 2017). "This would mean that any factor able to reduce the secretion of IL-6 could exert an anti-tumor action." (PMID 28356100, 2017). "Interestingly, tumor microenvironment produces cytokines, chemokines and growth factors, including TNFα, TGFβ, IL-6, FGF, epidermal growth factor (EGF), and HGF." (PMID 29088851, 2017). "Accordingly, in the murine experimental model of colitis-associated cancer (CAC), both the tumor multiplicity and growth were diminished in the absence of IL-17A, IL-6, IL-11 or TNF-α." (PMID 28881574, 2017). "Activated NF-κB is an effector of IL-6, which promotes neoplasia." (PMID 28570595, 2017). "We postulate that tumor cells may acquire migratory phenotype through the IL-6/IL-6R/STAT3 axis, and potent chemokines, such as CXCL8, initiate the actual cellular movement to a specific direction." (PMID 29245982, 2017). "Moreover, both TNF-α and IL-6 in the serum of the C57BL/6J (MyD88+/+) tumor-bearing mice stimulated by APS and LPS were obviously higher than those in NS and ADM groups (P< 0.05)." (PMID 28303957, 2017). "In vivo IL-6 and IL-8 secretion would stimulate neoangiogenesis to deliver oxygen and nutrients to the growing tumor whereas in vitro the result could be the increased microtumor growth and maintenance we observed during our validation studies." (PMID 29245949, 2017). "Sorafenib has predominant inhibition on tumor growth when IL-6 was knocked out (1026.6±56.0 mm3 versus 673.4±34.0 mm3, P=.027) based on treatment, whereas IFN-α treatment significantly inhibited tumor growth in the HCC derived from HCCLM3-wt cells (4565.2±213.3 mm3 versus 1730.2±169.3 mm3, P =.021)." (PMID 29100435, 2017). "In addition to its direct effects on cell proliferation, NF-κB can alter tumor growth and progression through activation of its target genes, including IL-6, VEGF, MMP9 and TNF- α." (PMID 28978058, 2017). "The function of neutrophils could be converted from tumor-suppressing to tumor promoting by G-CSF and IL-6." (PMID 28415700, 2017). "In addition, there is cross-talk between the SDF-1 subtype SDF-1α and IL-6 signaling, which promoted tumor cell proliferation and chemoresistance in PDAC." (PMID 29254283, 2017). "Mice with either 4T07 or 4T1 tumors had increased liver mRNA production of IL-1β (H = 34.10, p < 0.001), IL-6 (H = 29.12, p < 0.001), and TNFα (H = 35.31, p < 0.001) compared to either the vehicle or 67NR tumor-bearing mice (p < 0.05 in all cases, Dunn’s multiple comparisons)." (PMID 28811490, 2017). "IL-17 can promote tumor growth through an IL-6-Stat3 signaling pathway." (PMID 29190997, 2017). "Analyzing TCGA and CCLE expression data with GSEA, we confirmed indirectly the underlying biochemistry in human tumors samples by showing that expression of response genes for IFN and IL-6 families of cytokines are reduced in tumor samples and cell lines with JAK1 frameshifts." (PMID 29121062, 2017). "It has been proposed that inflammatory cytokines, such as interleukin-6, produced by tumour cells may stimulate the differentiation and proliferation of megakaryocytes to produce abundant giant platelets." (PMID 28152504, 2017). "Induction of angiogenesis and of tumor-promoting cytokines, as IL-6 and IL-8, might explain the pro-tumoral effect." (PMID 28829805, 2017). "However, increasing evidence shows that tumor cell-secreted IL-6 also promotes tumorigenesis through autocrine regulation." (PMID 28784136, 2017). "In addition to univariate analysis, a multivariate analysis of prognostic factors using logistic regression analysis was performed based on the following factors: tumor burden, progression, lymph node positivity and serum Shh and IL-6 levels." (PMID 28496132, 2017).
tumor (continued). "In addition, BZA markedly decreased IL-6-mediated tumor cell migration and cancer stem cell phenotype by inhibiting FAK activation and decreasing the expression of nanog." (PMID 28978005, 2017). "Interestingly, Il6 and Tnfa, which can be both pro-inflammatory and tumor-promoting, were significantly upregulated in macrophages exposed to conditioned media as compared to control media." (PMID 28881599, 2017). "Tumor-secreted inflammatory mediators such as Interleukin 6 (IL-6) and Tumor necrosis factor α (TNF-α), can regulate host metabolism in multiple tissues, suggesting a possible role of an inflammatory state in mediating tumor-induced metabolic changes in the host." (PMID 28874144, 2017). "In addition, IL-6 exerts its tumour proliferative and anti-apoptotic potential by targeting genes involved in cell cycle progression and the suppression of apoptosis." (PMID 28764778, 2017). "Experimental studies demonstrated that IL-6 could promote proliferation, invasion and metastasis of tumor cells." (PMID 28977974, 2017). "The increase in IL-8 and MCP-1 was more rapid than that for IL-6 which could be explained by release of the latter from reacting tumor cells or infiltrating inflammatory cells recruited by the formers." (PMID 27664151, 2017). "We conclude that tumor cell migration towards blood vessels might be the result of endothelial cell-secreted factors working together, and that IL-6 primes the cancer stem cells to respond to these factors." (PMID 29245982, 2017). "Furthermore, we demonstrated that tumor-derived IL-6 was essential for MDSCs amplification and function in vitro, including promoting T cells apoptosis, inhibiting T cell proliferation, decreasing IFN-γ secretion, and increasing IL-10 production." (PMID 29326716, 2017). "There were studies showing that IL-6 production from macrophage could induce IL-6 secretion from tumor cells." (PMID 28088791, 2017). "Moreover, IL-6 contributes to the malignancy of tumor cells bysustaining the phosphorylation of signal transducer and activator of transcription 3(STAT3)." (PMID 28659496, 2017). "JAKs are key participants in signaling networks fueled by a variety of cytokine and growth factor receptors in the tumor microenvironment, including IL-6, IL-11, IL-27, interferon (IFN-α/β/γ) oncostatin M (OSM), leukemia inhibitory factor (LIF), epidermal growth factor (EGF) and others." (PMID 29190997, 2017). "Il6 deficiency also reduced hepatic mRNA levels of Stat3 target genes (Birc5, Bcl2l1 and Ccnd1), cyclins (Ccna2, Ccnb1, Ccnb2), and markers of proliferation (Mki67) and HCC (Afp) in livers from FGF19-expressing mice, further demonstrating the role of IL-6 in mediating FGF19-driven tumour growth." (PMID 28508871, 2017). "Irradiation caused higher expression of both IL-6 and TNF-α in tumour cells." (PMID 29070894, 2017). "In addition, IL6 modulates the balance between regulatory T cells and T helper 17 cells in the tumor microenvironment and promotes the generation of cancer stem cells from noncancer stem cells." (PMID 27163161, 2016). "IL-6 was shown to be an autocrine proliferation factor for tumor cell lines." (PMID 27190500, 2016). "It has been proposed that IL-6 produced by TAFs leads to inhibition of monocyte and macrophage differentiation and function, contributing to final immunosuppression and creation of tumor-promoting microenvironment." (PMID 27630452, 2016). "Furthermore, circulating levels of IL-6 were decreased 80.80% (P < 0.01) in Selumetinib-treated LLC mice vs. vehicle-treated tumor bearers." (PMID 28149280, 2016). "However, IL-6 is produced by a number of normal and transformed cell lines, which can either promote or inhibit the growth of tumor cells." (PMID 27313650, 2016). "Our results indicate that reduced VEGFR-3 levels could have a detrimental effect on the immunological anti-tumor response in an early stage of primary tumor growth, through impaired lymphangiogenesis and IL-6 elevation." (PMID 27329584, 2016).